IFI27 (interferon alpha inducible protein 27)
Diseases named in the same sentence as IFI27 in open-access papers (continued):
Sharing a sentence is not in itself a finding about the gene and the disease.
COVID-19 (continued). "Since these findings suggested that upper airway IFI27 expression levels do not have a strong prognostic value (and a limited dynamic range) we sought an alternative sampling route to measure IFI27 expression in COVID-19 patients." (PMID 36685600, 2022). "Therefore, we concluded that the IFI27, TUBB2A and the pathways of NET formation and lupus like immune profile may be the potential immune deregulation mechanism triggered by COVID-19, but further experimental validation in vitro and in vivo is needed." (PMID 34554255, 2022). "The intermediate monocytes (consistently present in COVID-19) were characterized by a pronounced antiviral, interferon-driven response, as illustrated by the upregulation of both interferon-inducible and stimulated genes (IFI6, IFI27, IFI44L, and ISG15, SIGLEC1)." (PMID 34424199, 2021). "In the meantime, IFI27 expression was below 6.2 in all of the 19 healthy controls (median value 1.0), while it was above 6.2 in 11 of the 35 non-hospitalized patients (31.4%) with COVID-19 (median value 4.3), and 11 of the 12 hospitalized patients (91.7%) with COVID-19 (median value 8.56)." (PMID 36649304, 2023). "In the gene expression validation experiment for the COVID-19 group, significant differences were viewed between the disease and normal groups for the IFIT3 and IFI27 genes, while no notable distinction was found in the EIF2AK2 gene." (PMID 38601162, 2024). "IFI6, ISG15, IFI27, and IFI35 were increased in mild, and decreased or not changed in severe COVID-19, compared to healthy controls." (PMID 34108966, 2021). "In the meantime, IFI27 expression was above 6.0 in 38 of the 50 non-ICU patients (76%) with COVID-19 (median value 8.11), and it was above 6.0 in 24 of the 50 ICU patients (48%) with COVID-19 (median value 5.74)." (PMID 36649304, 2023).
influenza (30 papers, 2012 to 2025). An acute viral infection of the respiratory tract, occurring in isolated cases, in epidemics, or in pandemics; it is caused by serologically different strains of viruses (influenzaviruses) designated A, B, and C, has a 3-day incubation period, and usually lasts for 3 to 10 days. "For example, de novo mutation in ATP6V1B2 was found to impair lysosome acidification and cause dominant deafness-onychodystrophy syndrome, while IFI27 was found to discriminate between influenza and bacteria in patients with suspected respiratory infection, among others." (PMID 36298522, 2022). "The top-ranked genes for influenza classification included IFI27, ZFP36L1, TNC, SERTAD2, and AMPD3, several of which are known interferon-stimulated or antiviral response genes." (PMID 41020849, 2025). "IFI27 has also been proposed as a biomarker to differentiate between influenza and bacterial respiratory infection, although its ability to distinguish between different viruses is limited." (PMID 40476695, 2025). "As mentioned in the introduction, ATP6V1B2 was found to impair lysosome acidification and cause dominant deafness-onychodystrophy syndrome, while IFI27 was found to discriminate between influenza and bacteria in patients with suspected respiratory infection." (PMID 36298522, 2022). "In the lung, IFI27 expression has also been suggested as a biomarker to differentiate influenza and bacterial infections." (PMID 35820705, 2022). "A single gene biomarker, IFI27, was used for discriminating between influenza and bacterial infections was identified using integrated genomic analysis." (PMID 35186993, 2022). "We have previously discovered that the transcription of the interferon alpha-inducible protein 27 (IFI27) is a signature marker of pandemic H1N1/09 influenza infection." (PMID 36685600, 2022). "IFI27 may, therefore, serve as a molecular biomarker in human blood to distinguish influenza and metapneumovirus from other respiratory infections." (PMID 39192977, 2024). "The differential temporal expression of MX1 and IFI27 in the SARS-CoV-2 challenge model was replicated in challenge experiments with multiple influenza strains, respiratory syncytial virus, or rhinovirus, and in data from household contacts with naturally acquired SARS-CoV-2 infection." (PMID 39616162, 2024). "IFI27 expression is also upregulated in the blood of patients suffering influenza infection, and IFI27 upregulation has been shown to be able to discriminate between influenza and bacterial respiratory infections." (PMID 37187533, 2023). "In vivo studies confirmed expression of IFI27 in influenza patients." (PMID 35186993, 2022). "This analysis confirmed that IFI27 upregulation occurred in severe influenza infection." (PMID 36685600, 2022). "However, IFI27 has been found to be the highest upregulated gene during both influenza and RSV infections." (PMID 32714913, 2020). "In influenza, IFI27 is upregulated and PI3 downregulated relative to human rhinovirus." (PMID 30271886, 2018). "Notably, IFI27 has also been shown to discriminate well between influenza and bacterial infections when measured using RT-PCR among people with suspected respiratory tract infection, further supporting its potential clinical utility for the detection of respiratory viruses." (PMID 34250515, 2021). "Our study found that IFI27 and OTOF protein levels were significantly reduced in children with influenza." (PMID 40718794, 2025). "The results of in-depth verification indicated that the hub genes IFI27 and OTOF found in children’s influenza were accurate." (PMID 40718794, 2025). "The influenza group’s validation experiment showed significant differences in all six genes (IFI44L, IFI44, RSAD2, IFIT3, EIF2AK2, and IFI27)." (PMID 38601162, 2024).
influenza (continued). "Their work showed that IFI27 is upregulated by TLR7 in plasmacytoid dendritic cells, more responsive to influenza virus than bacteria, and confirmed its expression in influenza patients through multiple patient cohorts." (PMID 39282474, 2024). "Among them, some had greater significance for influenza infection than others, such as IFI27 (also called ISG12) and IFITM3 (both are up‐regulated genes), have been reported widely and in details." (PMID 33448094, 2021). "The transcript levels of IFI27 and PI3 in these subjects were more similar to the non-influenza infection cases." (PMID 26070066, 2015). "Recently, interferon alpha-inducible protein 27 (IFI27) was found to be able to distinguish influenza and non-influenza flu-like illnesses in a large cohort, with an area under the curve (AUC) value of 0.87." (PMID 32714913, 2020). "In addition to IFI27 and PI3 that have the largest expression difference between influenza and HRV, CDKN1A and CDKN1C, which are essential genes involved in cell cycle control, appeared to be differentially expressed specifically in influenza virus infection." (PMID 26070066, 2015). "Jointly considering our new results at DNA methylation levels and the earlier discovery of IFI27 in COVID-19 infections, it may be safe to infer that the CpG site cg16785077 (MX1) played a role in SARS-CoV-2 transmissions and led to influenza-like symptoms through IFI27 (NP/OP)." (PMID 38666857, 2024). "However, it is important to note that IFI27 is non-specific for SARS-CoV-2, and is upregulated in response to other respiratory infections including H1N1/09 influenza and respiratory syncytial virus." (PMID 37063834, 2023).
breast carcinoma (17 papers, 2016 to 2025). "Besides, GBP1 and IFI27 were associated with the apoptotic biological process, and were related to breast cancer phenotype resistant to trastuzumab treatment." (PMID 32318098, 2020). "Its stabilization in esophageal cancer leads to tumor progression and angiogenesis, while in breast cancer, metastases showed systematic downregulation of IFI27." (PMID 37508582, 2023). "In a similar fashion, IFI27 overexpression was shown to impair the tamoxifen-induced apoptosis in breast cancer cells." (PMID 36497286, 2022). "They suggested that IFI27/ISG12 is an important factor in regulating ERα activity in breast cancer cells and a potential target of future strategies to control the growth and proliferation of ERα-positive breast cancer." (PMID 37435453, 2022). "IFI27 is highly expressed in several cancers, such as ovarian cancer, hepatocellular carcinoma, and breast cancer." (PMID 35267998, 2022). "IFI27 or ISG12a was first named as interferon alpha-inducing protein 27 (p27) in estradiol-treated MCF7 human breast carcinoma cells." (PMID 33868214, 2021). "The up‐regulation of IFI27 participates in the invasion and proliferation of oral squamous cell carcinoma, pancreatic ductal adenocarcinoma, and breast cancer." (PMID 33955587, 2021). "IFI27/ISG12 transcription is regulated by interferon and estradiol and its overexpression is associated to reduced overall survival in ER+ breast cancer patients but its function in mammary gland tissue remains elusive." (PMID 33117284, 2020). "Our studies identified a 122-amino acid protein, previously identified as interferon/estradiol induced p27/IFI27/ISG12 (hereafter ISG12) and which is overexpressed in breast cancer cells." (PMID 33117284, 2020). "In this study we showed that overexpression of IFI27/ISG12 in breast cancer cells attenuates ERα transactivation activity and the expression of ERα-dependent genes." (PMID 33117284, 2020). "IFI27 is suggested to be involved in proliferation of skin keratinocytes and up-regulated in breast cancer, SCC of the skin and ovarian cancer." (PMID 28038473, 2017). "In addition to our study, multiple studies have shown that IFI27 is highly expressed in several cancers, such as ovarian cancer, hepatocellular carcinoma, and breast cancer." (PMID 39457004, 2024). "Our results suggest that IFI27/ISG12 may be an important factor in regulating ERα activity in breast cancer cells by modifying its nuclear versus cytoplasmic protein levels." (PMID 33117284, 2020). "IFI27/ISG12 overexpression was shown to suppress the estradiol-dependent proliferation and tamoxifen-induced apoptosis in breast cancer cells." (PMID 37435453, 2022). "They revealed the interactions between endogenous ERα and IFI27/ISG12 in the cytoplasm, nucleus, and perinuclear region in breast cancer cell MCF-7, T47D, and ZR-75-1 cells." (PMID 37435453, 2022). "IFI27/ISG12 overexpression was shown to impair the estradiol-dependent proliferation and tamoxifen-induced apoptosis in breast cancer cells." (PMID 33117284, 2020). "The upregulation of IFI27 was first reported in the psoriasis model, and in recent years, it has been found that IFI27, together with LCN2, can be used as two basal breast cancer subtype markers." (PMID 29580248, 2018). "We studied the effect of resveratrol, genistein, apigenin and thymoquinone at non- toxic concentrations on the expression activation of type I IFN signaling genes (IFN-responsive genes IFI27 and OASL, and IFN regulatory factor IRF1) in another cell line, T47D (human breast cancer cells)." (PMID 39796235, 2025). "Differentially expressed genes, especially those in five modules, including OAS1, IFI27, LPAR1, PTGFR, ITGB4, and ITGA6, might participate in the epithelial-mesenchymal transition process in breast cancer cell line DKTA." (PMID 36289533, 2022). "We propose that IFI27/ISG12 may be a potential target of future strategies to control the growth and proliferation of ERα−positive breast cancer tumors." (PMID 33117284, 2020).
breast carcinoma (continued). "The expression of IFI27 and IFI6 is upregulated in epithelial malignancies, breast cancer, and ovarian cancer, and their expression may be abundant in cancer cells." (PMID 27629773, 2016).
ovarian carcinoma (15 papers, 2014 to 2025). A malignant neoplasm originating from the surface ovarian epithelium. "In ovarian cancer IFI27 is associated with patient survival where high IFI27 expression correlates with poor disease free survival." (PMID 28038473, 2017). "Similar findings have been reported on the drug resistance and epithelial–mesenchymal transition of IFI27 in ovarian cancer." (PMID 36232317, 2022). "In this respect, it appears of interest that the induction of the ISG IFI27 in ovarian carcinoma biopsies and cell lines drives EMT, cancer stemness, invasiveness and therapeutic resistance." (PMID 36002648, 2022). "There are also reports revealing that overexpression of IFI27 can induce epithelial–mesenchymal transition and promote the tumorigenicity, migration and invasion, stemness and drug resistance of epithelial ovarian cancer cells." (PMID 34592906, 2021). "IFI27 expression was elevated in the psoriatic lesions and uterine fibroids, ovarian cancer, and other diseases." (PMID 33419394, 2021). "IFI27 not only induced ovarian tumorigenicity, stemness, but also participated in drug resistance of ovarian cancer cells." (PMID 32592372, 2020). "Overexpression of IFI27 has been shown to induce drug resistance in ovarian cancer cells." (PMID 40224214, 2025). "In addition, multiple studies have shown that IFI27 is highly expressed in a number of cancers, such as ovarian cancer, hepatocellular carcinoma and breast cancer." (PMID 34592906, 2021). "Moreover, IFI27 overexpression could induce epithelial-mesenchymal transition and promote migration, invasion, tumorigenicity, stemness, and drug resistance in ovarian cancer cells." (PMID 31321241, 2019). "Treatment of the ovarian cancer cell line A2780, for 72 hours with 500 nM carboplatin does not lead to overexpression of AIM genes IFI27, IRF7, IL15, or MAGEB2, all of which are increased in AZA-treated cells." (PMID 24583822, 2014).
Sepsis (14 papers, 2016 to 2026). Sepsis is defined as life-threatening organ dysfunction caused by a dysregulated host response to infection. "It is possible that IFI27 might participate in the mechanisms underlying immunodeficiency, and the expression of IFI27 might be associated with sepsis exacerbation, therefore representing a potential therapeutic target." (PMID 37749550, 2023). "However, the relationship between IFI27 and Treg-mediated regulation in sepsis-associated lung injury remains unclear." (PMID 42099627, 2026). "As an additional comparison, S100A12 expression was above 8.0 in 39 of the 42 sepsis patients (92.9%, median value 10.23), while IFI27 expression was above 4.5 in only 10 of these 42 sepsis patients (23.8%, median value 1.94)." (PMID 36649304, 2023). "In summary, our study identified five key genes including NKG7, SPTA1, FGL2, RGS2, and IFI27, which were closely related to the sepsis-induced ARDS development." (PMID 34393665, 2021). "Experiments in IFI27-deficient mice indicated that a lack of IFI27 prolongs survival in experimental sepsis and endotoxemia." (PMID 33388093, 2021). "Therefore, activation of S100A12 could be even stronger in sepsis, but it was infrequently accompanied by the activation of IFI27 (except for viral sepsis)." (PMID 36649304, 2023). "Within the GSE42026 validation set, there was a significant difference (P < 0.01) in the expression of IFI27 and OTOF between the pediatric sepsis and control groups." (PMID 40718794, 2025). "In the sepsis group, the genes related to significant AS events, such as, SHISA5 and IFI27, were mostly enriched in the cell apoptosis pathway." (PMID 37749550, 2023). "We observed that IFI27 and SHISA5, both apoptosis-related genes, were controlled by the 5pMXE AS pattern and showed significant differential expression levels in sepsis when compared to the healthy group and the infection group." (PMID 37749550, 2023). "Five genes (NKG7, SPTA1, FGL2, RGS2, and IFI27) have been proved to be potential biomarkers for sepsis-induced ARDS and exert crucial roles in the occurrence and development of sepsis." (PMID 36299685, 2022). "Mechanistically, IFI27 suppresses Treg function and enhances ferroptosis in lung epithelial cells through inhibition of the IL-10/STAT3 signaling pathway, thereby aggravating sepsis-induced lung injury." (PMID 42099627, 2026). "In vivo, IFI27 expression was examined in a cecal ligation and puncture (CLP) mouse model, and an IFI27 overexpression mouse model was used to evaluate its functional role in sepsis." (PMID 42099627, 2026). "IFI27/ISG12 is a novel modulator of innate immune responses that regulate anti-inflammatory nuclear receptors, and experiments using IFI27/ISG12 deficient mice revealed that a lack of ISG12 prolongs survival in experimental sepsis and endotoxemia." (PMID 27100186, 2016). "Furthermore, five genes including NKG7, SPTA1, FGL2, RGS2 and IFI27 exhibited significant differences between the sepsis-induced ARDS samples and the samples with sepsis alone in two datasets, suggesting that these five genes might be key genes that led to sepsis patients complicated with ARDS." (PMID 34393665, 2021). "Moreover, five genes including NKG7, SPTA1, FGL2, RGS2, and IFI27 exhibited notable difference between the sepsis-induced ARDS group and the control group with sepsis alone in two datasets, suggesting that these five genes might be key genes that led to sepsis patients complicated with ARDS." (PMID 34393665, 2021).
systemic lupus erythematosus (12 papers, 2011 to 2025). An autoimmune multi-organ disease typically associated with vasculopathy and autoantibody production. "As an interferon-α inducible protein, IFI27 was confirmed to be up-regulated in PBMCs of systemic lupus erythematosus patients and in the lungs after influenza A infection in mice, mainly due to the infiltration of macrophages and lymphocytes." (PMID 33388093, 2021). "IFI27 is an interferon-α inducible protein that is up-regulated in PBMCs of systemic lupus erythematosus patients and in the lung after influenza A infection in mice, mainly due to the infiltration of macrophages and lymphocytes." (PMID 27100186, 2016). "IFI27 is up-regulated in PBMCs of systemic lupus erythematosus patients and in inflammatory psoriatic skin and in some epithelial cancers." (PMID 27100186, 2016). "A recent study demonstrated that IFI27 is more likely to be upregulated in lupus than in another autoimmune condition, idiopathic thrombocytopenic purpura." (PMID 21366908, 2011). "Many genes contained in the Hallmark IFN-α response and Hallmark TNF-α signaling pathways, including IFI27, IFI44, RELB, KLF6, and CD83, had significantly higher expression in lupus: We verified transcriptional changes in the naive compartment by quantitative PCR (qPCR)." (PMID 39688922, 2024). "In addition, IFI27 was previously identified as a marker of epithelial cancers and psoriatic lesions and related to systemic lupus erythematosus (SLE)." (PMID 28558652, 2017). "In addition to being the most highly-upregulated of the IFN genes in our sample, other data suggest that IFI27 is relatively more specific for lupus than at least some of the other IFN-inducible genes." (PMID 21366908, 2011). "The results showed that IFI27 and LAMP3 were mainly enriched in cell cycle, Systemic Lupus Erythematosus, cytosolic DNA sensing pathway, toll-like receptor (TLR) signaling pathway and nod-like receptor (NLR) signaling pathway." (PMID 40297850, 2025). "Four proteins, SNRPB/SNRPN, OGN, IFI27, FBLN2, identified only in extracellular vesicles in the blood of CLE patients were also proteins reported to be related to lupus and inflammation." (PMID 41614843, 2025). "It has also been reported that IFI27 may play a vital role in the occurrence of systemic lupus erythematosus (SLE), and may be a possible target for SLE diagnosis." (PMID 35651940, 2022).